CD14 (CD14 molecule)
Diseases named in the same sentence as CD14 in open-access papers (continued):
Sharing a sentence is not in itself a finding about the gene and the disease.
Sepsis (continued). "The baseline and LPS-stimulated TLR4 expression on the CD16- (classical) monocytes were not different between variant and wild-type allele carriers of TLR4+896A/G or CD14-159C/T as well as between non-severe sepsis and severe sepsis cases (data not shown)." (PMID 27861595, 2016). "Nonetheless, the magnitudes of these LPS-stimulated changes were not different between variant and wild-type TLR4+896A/G or CD14-159C/T allele carriers as well as between non-severe sepsis and severe sepsis cases." (PMID 27861595, 2016). "In febrile acute de-compensated cirrhotic patients, TLR4+896A/G and CD14-159C/T polymorphisms-related non-classical and classical monocytes dysfunction resulted in increased severe sepsis risk." (PMID 27861595, 2016). "This investigation addresses the hypothesis that sepsis patients with the TT genotype of CD14 rs2569190 may have an improved 30-day survival compared with patients carrying the C allele." (PMID 26020644, 2015). "In conclusion, CD14 rs2569190 may act as a prognostic variable for the short-term outcome (30-day survival) in patients with sepsis." (PMID 26020644, 2015). "In this study, we hypothesized that the strong pro-inflammatory response induced by the TT genotype of CD14 rs2569190 may have a beneficial effect on survival (30-day) in patients with sepsis." (PMID 26020644, 2015). "Given that CD14 may play an essential role in the pro-inflammatory response, we hypothesized that the strong pro-inflammatory response induced by the TT genotype of CD14 rs2569190 may improve survival (30-day) in patients with sepsis." (PMID 26020644, 2015). "Presepsin (soluble CD14 subtype) has been shown to be beneficial as a sepsis marker in adults." (PMID 26720209, 2015). "In addition, TLR2 and CD14 were analyzed as representatives of the pattern-recognition receptors which represent another system that was upregulated in sepsis patients of the discovery set." (PMID 26607226, 2015). "Indeed, we observed a significant enrichment of CD14+HLA-DRlow/- monocytes in the peripheral blood, as well as within the total monocyte pool, in patients with sepsis." (PMID 25992611, 2015). "Studies have shown that genetic polymorphisms of these SNPs can affect CD14 gene expression as well as the level of soluble CD14 in serum, and that this might be involved with the occurrence of sepsis and the subsequent prognosis of the disease." (PMID 25394369, 2014). "The observed association of higher susceptibility to sepsis among TLR4 rs11536889 and CD14 rs2563298 genotypes may help intensive care specialists to identify patients at risk of developing sepsis." (PMID 25394369, 2014). "Numerous studies have indicated that LPS triggers pathogenesis of sepsis by recognizing TLR4 (Toll-like receptor 4) and CD14 on the surface of cells; so an effective way to prevent sepsis could be by neutralizating LPS." (PMID 24654965, 2014). "Thus, we compared three newly developed synthetic anti-lipopolysaccharide peptides (SALPs) with a broader range of efficacy to suppress cytokine release in plasma and CD14 mRNA expression in organ tissue in a murine, polymicrobial sepsis model." (PMID 23302299, 2013). "Similarly, Pep2.5 significantly reduced the sepsis-induced CD14 mRNA expression in heart (P = 0.003), lung (P = 0.008), and spleen tissue (P = 0.009) but not in kidney and liver." (PMID 23302299, 2013). "Taken together, these results suggest that CD14 may play a pivotal role in the pathogenesis of sepsis." (PMID 23990939, 2013). "Furthermore, inflammation indicated by cytokines in plasma and CD14 expression in organ tissue should be decreased in a murine model of polymicrobial sepsis." (PMID 23302299, 2013). "However, this study demonstrates for the first time that TLR9 and CD14 play a major role in the development of vascular dysfunction in polymicrobial sepsis." (PMID 22970242, 2012). "TLR and CD14 protein expression on monocytes of patients with sepsis according to survival." (PMID 19371402, 2009).
Sepsis (continued). "Death due to sepsis is associated with TLR2 and CD14 downregulation." (PMID 19371402, 2009). "Complement and Toll-like receptors, including the CD14 molecule, are two main upstream recognition systems of innate immunity, contributing to the inflammatory reaction in a number of conditions including ischaemia-reperfusion injury and sepsis." (PMID 18419792, 2008). "In other studies involving primarily Caucasian adults, the CD14 -260 C/T polymorphism does not seem to have a major influence on the risk for or outcome from sepsis." (PMID 16611358, 2006). "Variation in the IL-10, IL-6 and CD14 genes may be genetic factors influencing the development and outcome of sepsis in the premature newborn." (PMID 16611358, 2006). "To acquire further evidence to establish whether neutrophil-like monocytes were expanded in acute human sepsis, we interrogated publicly available RNAseq datasets of bulk human CD14+ monocytes from patients with sepsis for evidence of a neutrophil-like gene signature." (PMID 40475424, 2025). "Presepsin is a monocyte-derived soluble subtype of CD14 (sCD14-ST), specifically a 13 kDa N-terminal fragment produced by cathepsin D. It plays a key role in activating the innate immune response and has emerged as a biomarker for the early diagnosis and monitoring of sepsis." (PMID 41153245, 2025). "However, the monocyte CD14 (mCD14) has limited diagnostic efficiency and a monitoring role for sepsis, and is therefore not suitable for use as a septic biomarker in NICUs." (PMID 40626122, 2024). "Notably, the proportion of CD14+ monocytes (CD14 Mono) was significantly increased in sepsis." (PMID 39578684, 2024). "Previous study reported that elevated levels of soluble CD14 in different fluids can be detected during sepsis, The findings of this study are consistent with previous reports that elevated levels of soluble CD14 in different fluids can be detected during sepsis." (PMID 36650427, 2023). "Notably, we observed a decrease of both CD8 and CD16 markers for CD8+ T and NK cells, respectively, in sepsis, which could be associated with the high expression of the P2X7 receptor, as was previously observed for the monocytic marker CD14 in sepsis." (PMID 38094297, 2023). "Interestingly, Subtype of CD14, presepsin, is an emerging and reliable biomarker of sepsis." (PMID 34630395, 2021). "During sepsis, cell-free CD14 is present in serum and other body fluids and has been proposed as a marker for septic patients; in fact, the presence of CD14 in the blood has been validated by different studies as a valuable prognostic capacity to predict mortality." (PMID 33135636, 2020). "Skjeflo and coworkers demonstrated that simultaneous upstream inhibition of complement and CD14 efficiently attenuated S. aureus-induced inflammation in a human whole-blood model, suggesting that double blockade might be a promising treatment of sepsis." (PMID 31964768, 2020). "In the same study, combined inhibition of complement C5 by OmCI and CD14 with anti-CD14 antibodies significantly attenuated inflammation, thrombogenicity, and hemodynamic abnormalities, suggesting OmCI might be useful for the treatment of sepsis." (PMID 33072132, 2020). "As previously reported, lower frequencies of CD14+ monocytes expressed HLA-DR in patients with sepsis compared to control subjects (p<0.0001), and patients with infections only (p = 0.038), potentially accounting for the observed failure of lymphocyte activation in patients with sepsis." (PMID 31658288, 2019). "Second, this study focused only on the CD14 polymorphism regardless of the likelihood that other genetic variations may also influence sepsis risk and mortality." (PMID 28122493, 2017). "Not surprisingly, in our TLR4+896A/G and CD14-159C/T variant alleles carriers with severe sepsis, increased TLR4 expression was accompanied by the up-regulation of in vitro LPS-stimulated NFκB, TNF-α, and iNOS signals on their cultured non-classical (CD16+, inflammatory) monocytes." (PMID 27861595, 2016).
Sepsis (continued). "In addition to regular predictive factors such as malnutrition, high plasma endotoxin and sCD14 levels for development of severe sepsis in high risk groups, the novel predictive factors were either single or double TLR4+896A/G and CD14-159C/T variant alleles carriers observed in current study." (PMID 27861595, 2016). "This is in accordance with our present findings in polymicrobial sepsis where complement activation was completely abolished in the treated group, which probably is a main explanation for the reduced IL-8 release, although an additional effect of blocking CD14 is likely for both mediators." (PMID 26612199, 2015). "However, the concomitant presence of reduced proportions of CD14+ HLA-DR cells with elevated levels of neopterin was reported in trauma patients and sepsis, together proposed as biomarkers reflecting an immune response, not balanced, susceptible to favors sepsis and adverse MOF." (PMID 24594915, 2014). "In addition to CD14 rs2569190-GG, one SNP of the IL8 gene was also associated with severe sepsis." (PMID 25000179, 2014). "This meta-analysis suggests that the CD14-159C/T polymorphism may not be a significant susceptibility factor in the risk of sepsis and mortality." (PMID 23990939, 2013). "The results of this meta-analysis suggest that the CD14-159C/T polymorphism may not significantly influence the risk for sepsis in overall populations." (PMID 23990939, 2013). "We hypothesized that TLR and CD14 expression is increased in sepsis, but inadequately less increased in severe sepsis compared to nonsevere sepsis, possibly associated to monocyte hyporesponsiveness." (PMID 19371402, 2009). "The CD15+CD14+ monocytes and CD45RA−CX3CR1+CTLA4+CD4+ T cells were only significantly increased in children with sepsis in those >1 year of age." (PMID 40433376, 2025). "There was a progressive increase in the frequency of the CD15+CD14+ monocytes, CD45RA−17A+CD4+ T cells, and CD45RA-CX3CR1+CTLA4+CD4+ T-cell subsets from control to sepsis with organ dysfunction." (PMID 40433376, 2025). "The study elucidates the critical role of protective immune cell phenotypes, such as CCR2 + CD14 − CD16 + monocytes and HLA-DR + NK cells, in modulating sepsis progression through coordinated innate and adaptive immune responses." (PMID 40797460, 2025). "Here, we found that these DEGs are primarily enriched in IL1B+ macrophages or CD14+ monocytes from IBD and sepsis patients." (PMID 39993996, 2025). "This study found that CREB5 was significantly upregulated in sepsis, and was specifically enriched in CD16+ and CD14+ monocytes, and its expression level showed dynamic changes with cell differentiation." (PMID 41246299, 2025). "Consistent with our findings, they found an increased proportion of CD14+ monocytes and decreased proportions of CD4+ T cells, CD8+ T cells, NK cells and mDC cells in sepsis." (PMID 40486505, 2025). "In macrophages, the most differentially expressed genes after sepsis include S100a9, S100a8, Hbb-bs, Fth1, AW112010, Spic, Cxcl2, Cd14, Hmox1, and Vcam1." (PMID 38343542, 2024). "Our study provides a theoretical basis for CD14 and CD163 as new biomarkers for predicting sepsis in children." (PMID 40626122, 2024). "Presepsin, also referred to as CD14 (cluster-of-differentiation) functions, a receptor for peptidoglycan with PCT, has a comparable performance with diagnosing sepsis in the ED." (PMID 36878489, 2023). "Hence, the increasing MO1/monocyte (CD14 + + CD16 −) percentage in septic shock and 28-day survival patients in our study revealed early excessive inflammatory response in older adult patients with sepsis is an important underlying factor contributing to its severity and poor prognosis." (PMID 36721090, 2023). "CD14 has recently been shown to be an important, highly cell-specific mediator of TNF response in a mouse sepsis model." (PMID 38065997, 2023).
Sepsis (continued). "Despite similar changes of the monocyte subsets including CD14+ and CD33+ in obese septic patients with diabetes, CD16 expression densities were higher in sepsis patients than in the non-sepsis group." (PMID 36687421, 2022). "Within the sepsis-related ARDS cohort, there appear to be two distinct subpopulations of BAL CD14+ EV numbers: “high” and “low”." (PMID 35234046, 2022). "The NF-κB signaling pathway is one of the key regulatory pathways of inflammatory response, and the changes in the expression of pathway-related genes such as CD14, MyD88, TNF-α, IL-1β, and IL-1R play an important role in the development of sepsis." (PMID 35186224, 2022). "Generally, CD14+CD16+ monocyte expansion was found in various diseases including obesity, diabetes, and sepsis compared with healthy controls." (PMID 36687421, 2022). "According to the Cohen’s effect size scale, the decline in percentage of the CD14+ monocytes and the CD33+ monocytes constituted the most significant parameters in obese patients suffering from sepsis including septic shock." (PMID 36687421, 2022). "In patients with sepsis-related ARDS, those who died within 30 days of intensive care unit (ICU) admission had a greater number of CD14+/CD81+ BAL EV than survivors (medians 3.43 × 108/mL vs. 9.54 × 107/mL, P = 0.027), however there is overlap between groups." (PMID 35234046, 2022). "Complement and/or CD14 inhibition successfully reduced the IFN-γ production in mice and baboons’ sepsis studies, thus preventing STAT1 and KLF4 overactivation." (PMID 36059503, 2022). "Both circulating G-MDSCs and M-MDSCs were noted with significant increases at the early stage of sepsis, which were defined as CD14-CD15+ and CD14+CD15- HLA-DR–/low, respectively." (PMID 35619710, 2022). "Decreased percentages of CD163+CD14+ monocytes and increased monocytic CD163 were observed in type 2 diabetes and obesity, as well as in sepsis patients." (PMID 36687421, 2022). "The relationship between CD14+/CD81+ BAL EV and mortality in patients with sepsis-related ARDS is in keeping with previous studies showing that the degree of monocyte influx in ARDS can correlate with the severity of respiratory failure." (PMID 35234046, 2022). "Collectively, these results indicate that when the level of NETs increase in the blood owing to sepsis or SLE, monocytes/macrophages phagocytose NETs that express high CD14 levels on their cell surface." (PMID 35396366, 2022). "A fraction of the soluble form of CD14, named soluble CD14 subtype (sCD14-ST) or presepsin (PSEP), has received increasing attention over the past 10 years as a possible early marker of sepsis." (PMID 34068959, 2021). "Among the seven immune cell subsets investigated, proportions of CD14+ monocytes, CD4+ T cells, CD8+ T cells, mDCs, and NKs were significantly altered in sepsis compared to HC." (PMID 33828550, 2021). "There was a trend toward increased proportion of CD14+ monocytes and decreased proportions of CD4+, CD8+ T cells, and NK cells in sepsis as compared to HC." (PMID 33828550, 2021). "Using chromatin from isolated CD14++ monocytes, ChIP experiments and subsequent qPCR revealed a differential CTCF occupancy at the investigated sites during postoperative sepsis." (PMID 33939725, 2021). "After in vitro culture of monocytes from sepsis patients, PGE2 diminished CD14+CD16+ monocytes after 24 h, reduced TNF‐α production, but enhanced anti‐inflammatory IL‐10 production." (PMID 32700336, 2020). "Biomarkers of sepsis so far evaluated in horses include interleukin-1β (IL-1β), interleukin-10 (IL-10), interleukin-6 (IL-6), serum amyloid A (SAA), soluble CD14 (sCD14) and procalcitonin." (PMID 33148245, 2020). "We found that glycogen levels in CD14+ monocytes were higher in SIRS and sepsis patients compared to healthy donors." (PMID 32286295, 2020). "Levels of CD14+ CD16+ monocytes, and Th, Tc + CD8α+ γδ T lymphocytes, and Treg lymphocytes decreased in time due to sepsis in both experimental groups." (PMID 32117276, 2020).
Sepsis (continued). "Binding of LPS to CD14 leads to the activation of immune cells and excessive production of TNF-α, playing a critical role in sepsis." (PMID 32230846, 2020). "The levels of CD14++CD16+, CD14+CD16++, and CD14++CD16– monocytes from 23 patients in the early phase of severe sepsis or septic shock as well as 25 healthy volunteers were determined via flow cytometry after coculture with or without ASCs." (PMID 28446249, 2017). "Our study also revealed that ASCs reduced the CD14++CD16+ phenotype, while increasing levels of CD14++CD16– monocytes from sepsis patients." (PMID 28446249, 2017). "Levels of proinflammatory CD14++CD16+ monocytes correlate with APACHE II and SOFA scores in the early phase of severe sepsis and septic shock." (PMID 28446249, 2017). "Monocytes were analyzed for expression of CD14, CD16 and HLA-DR in 10 controls and in 9 sepsis patients (validation cohort)." (PMID 28771573, 2017). "To determine the effects of ASCs on monocytes from sepsis patients, we cocultured the two cells types in vitro for 24 h and found that the CD14++CD16+ phenotype was decreased, while CD14++CD16– expression was increased." (PMID 28446249, 2017). "After confirming that TLR4 and CD14 are critical in transducing sepsis mediated ALI, we now demonstrate that intrapulmonary αvβ3 is increased by polymicrobrial sepsis in a TLR4, CD14 dependent fashion." (PMID 27349568, 2016). "Although CD86 was expressed on virtually all CD14+ monocytes, the expression was substantially decreased in a subpopulation of patients with LRR/MBC as well as in patients with sepsis." (PMID 25992611, 2015). "Since CD14+CD16+ monocytes are markedly expanded in cancer patients repeatedly treated with LPS and in sepsis patients, it has been suggested that the increase in cytokines caused by LPS or septicemia contribute to the induction of CD16 on monocytes." (PMID 25329467, 2014). "A strong increase of CD14 after LPS challenge and in CLP sepsis was noted in kidney tissue, predominantly in proximal tubular cells." (PMID 23302299, 2013). "In patients with sepsis, the percentages of cells expressing CD163 was higher in CD14++CD16− (median: 29.6%) and CD14++CD16+ (median: 27.00%) subsets than in the CD14+CD16+ subset (median: 0.00%)." (PMID 22693573, 2012). "TLR2-D animals are more prone to polymicrobial sepsis, presumably due to up-regulation of TLR4, 9 and CD14." (PMID 22970242, 2012). "As shown by other investigators before, CD14, TLR2 and TLR4 protein expression on monocytes is elevated during sepsis." (PMID 19371402, 2009). "Protein expression of CD14, TLR2 and TLR4 on blood monocytes was examined using flow cytometry from 29 patients with sepsis and 14 healthy controls." (PMID 19371402, 2009). "We found an increased expression of CD14, TLR2 and TLR4 in patients with sepsis compared to controls (p < 0.01)." (PMID 19371402, 2009). "In the complex pathogenesis of sepsis, CD16+/CD14+ monocytes play a central role in their functional reprogramming and abnormal association with multiple signaling pathways, including cytoskeletal regulation, metabolism, proliferation and inflammatory signaling pathways." (PMID 41246299, 2025). "This suggests that a high CD14+/CD81+ sEVs count found in patients’ body fluids could be a potential biomarker for the severity of disease and mortality in sepsis-related ARDS." (PMID 41010852, 2025). "Existing AF literature implicates inflammatory pathways and monocyte activation (including CD14-related markers), whereas presepsin has mainly been studied in sepsis and cardiometabolic contexts without AF endpoints." (PMID 41149083, 2025). "To explore whether CD38 drove dysfunctional activation of inflammation in monocytes of sepsis, we detected an induction of CD38 expression in primary CD14+ monocytes upon LPS and IFN‐γ stimulation and performed bulk RNA‐sequencing." (PMID 40145840, 2025).